ADAM10 (ADAM metallopeptidase domain 10)
Diseases named in the same sentence as ADAM10 in open-access papers (continued):
Sharing a sentence is not in itself a finding about the gene and the disease.
Alzheimer disease (continued). "The activation of ADAM10 by meprin β is of special interest in relation to the development of Alzheimer′s disease." (PMID 22940918, 2013). "5-HT4Rs are also implicated in Alzheimer’s disease, where they play a role in interacting with the alpha-secretase ADAM10, promoting non-amyloidogenic cleavage of the amyloid precursor protein and thus preventing pathological amyloid plaque formation." (PMID 40869038, 2025). "Therefore, the positive regulation of ADAM10 activity as a therapeutic strategy for Alzheimer’s disease has great potential that needs to be further evaluated." (PMID 38248261, 2024). "In this publication, the authors screened an FDA-approved drug libraryand identified 1 as a novel ADAM10 gene expression enhancer.In fact, 1 increased ADAM10 production in human neuronalcells in vitro and in peripheral blood cells in amouse model of Alzheimer’s disease." (PMID 38116411, 2023). "About the effect of this ADAM‐10 SNP in other disease, a previous study revealed the correlation between ADAM‐10 SNP rs2305421 G variant and late‐onset Alzheimer's disease, and another study also found the possible relationship between the ADAM‐10 SNP rs2305421 G and Alzheimer's disease." (PMID 36946281, 2023). "Since obesity is closely related to T2DM, and Alzheimer’s disease (AD) is also recognized as “type III diabetes,” we checked the expression of genes encoding proteins that are involved in amyloid-beta (Aβ) generation (ADAM10, BACE1, PSEN2, and GSK3β)." (PMID 37432552, 2023). "As such, ADAM10 is related to Alzheimer’s disease and neurodevelopment." (PMID 37240249, 2023). "In addition, it was upregulated in the hippocampus of Alzheimer disease patients where it acts on ADAM10 and it seems to be a biomarker for cellular senescence as well as for several neurodegenerative diseases." (PMID 37584866, 2023). "The Alzheimer's disease may be retarded by ADAM‐10 which can reduce the generation of amyloid‐β peptides, and the ADAM‐10 SNP rs2305421 is related to late‐onset Alzheimer's disease." (PMID 36946281, 2023). "However, regulators of ADAM10 expression have been described in the context of Alzheimer’s disease, where the protease exerts beneficial effects." (PMID 36498834, 2022). "ADAM10 might also be a potential blood biomarker for Alzheimer disease because it is the major alpha‐secretase that cleaves amyloid precursor protein in neurons." (PMID 35705192, 2022). "However, our data have demonstrated that caution needs to be exercised if systemic ADAM10 level is being considered as a potential biomarker for other conditions like Alzheimer disease in individuals with diabetes." (PMID 35705192, 2022). "It has been shown that abnormalities in the proteolytic activity of ADAM10 may play a pathophysiological role in conditions like Alzheimer disease, atherosclerosis, and inflammatory and malignant disorders." (PMID 35705192, 2022). "ADAM10 may play significant roles in neuronal functions and in the pathogenesis of Alzheimer’s disease." (PMID 35954348, 2022). "ADAM10 is a multifunctional protease and has been evaluated as a potential therapeutic target and biomarker because of its involvement in the pathogenesis of Alzheimer disease, atherosclerosis, and inflammatory and neoplastic disorders." (PMID 35705192, 2022). "Indeed, over-expression of ADAM10 in the neurons of a mouse Alzheimer’s disease model reduces amyloid β production and deposition in plaques, while over-expression of a catalytically inactive ADAM10 has the opposite effect." (PMID 34201472, 2021). "In Alzheimer’s disease, ADAM10 activation has the potential to inhibit disease progression, because ADAM10 cleavage of amyloid precursor protein (APP) prevents the generation of the pathogenic amyloid β peptide, which can otherwise be produced by β- and γ-secretases cleaving at alternative sites." (PMID 34201472, 2021).
Alzheimer disease (continued). "However, in Alzheimer's disease, ADAM10 facilitates autophagy in cleaving and removing abnormal proteins, demonstrating a neuroprotective effect." (PMID 34426753, 2021). "Several miRs have been associated with ADAM10 and c-Met: previous reports showed that miR122 down-regulates ADAM10 expression in breast cancer and hepatocellular carcinoma, while miR144 may play a role in down-regulating ADAM10 expression in Alzheimer disease." (PMID 32512881, 2020). "It is important to note, that for some indications (e.g., Alzheimer’s disease) molecules that induce or potentiate ADAM10 activity are thought to be needed, whereas for the majority of other indications (e.g., cancer, inflammation) the inhibitors of activity are sought after." (PMID 32435655, 2020). "Dysregulation of the disintegrin-metalloproteinase ADAM10 may contribute to the development of diseases including tumorigenesis and Alzheimer’s disease." (PMID 30753537, 2019). "Such an approach could provide new treatments for ADAM10-associated diseases, including T-ALL, asthma, atherosclerosis, and Alzheimer’s disease." (PMID 30013551, 2018). "Finally, the scavenger receptor TREM2 has been recently identified as an ADAM10 substrate with a potential role in Alzheimer’s disease." (PMID 30013551, 2018). "One of the major substrates of Adam10 is amyloid precursor protein (APP), for which Adam10 acts as an α-secretase to prevent the excessive production of the pathogenic amyloid β (Aβ) peptide, a hallmark of Alzheimer’s disease (AD)." (PMID 30075790, 2018). "This study assesses whether ADAM10 is present in cerebrospinal fluid (CSF), and whether it has potential as a biomarker for Alzheimer’s disease (AD)." (PMID 30045733, 2018). "Recent findings suggest that altered function of ADAM10 could contribute to neurodegenerative disease processes such as Alzheimer’s disease and encephalopathies." (PMID 27549131, 2016). "One mechanistic role for RARα signaling in preventing amyloid-β accumulation at the onset of Alzheimer's disease is by increasing Notch related α-secretase activity via a direct induction of ADAM10, and Alzheimer's-like defects are indeed suppressed by RARα agonists in a transgenic mouse model." (PMID 22396766, 2012). "From other reports it is evident that manipulation of ADAM10 in embryonic or early ontogenic stages could have severe side effects but therapeutic approaches concerning Alzheimer's disease always will focus on adult patients." (PMID 19196476, 2009). "ADAM10 has been best characterized in the context of early neural development, synapse function and the non-amyloid pathway which prevents accumulation of neurotoxic Aβ peptides—hallmarks of Alzheimer’s disease (AD)—and generates potentially neuroprotective APP α-fragments." (PMID 33791311, 2021). "Besides, various gene mutations closely associated with mitochondrial function, including those involving amyloid precursor protein (APP), presenilin 1 (PSEN1), 46 presenilin 2 (PSEN2), apolipoprotein E (ApoE) and a disintegrin and 71 metalloprotease 10 (ADAM10), lead to Alzheimer’s disease." (PMID 33686350, 2021). "Interestingly, extracellular α-synuclein may downregulate the expression of ADAM10, whose role has been already established in Alzheimer’s disease pathogenesis." (PMID 32340360, 2020). "ADAM10 might be best known historically for its role in Notch signaling, and more recently for cleaving the amyloid precursor protein (APP) associated with the pathophysiology of Alzheimer's disease." (PMID 32265938, 2020). "ADAM10 is a member of the ADAM metalloprotease family, which is a key proteinase responsible for the processing of amyloid precursor protein (APP) to prevent the excessive production of the pathogenic amyloid β (Aβ) peptide, a hallmark of Alzheimer’s disease (AD)." (PMID 31114485, 2019).
Alzheimer disease (continued). "Proteins known to be involved in Alzheimer’s disease progression, (such as CLU, APOE, and ADAM10) and Parkinson’s Disease (such as PARK7 and VPS35) were also identified, suggesting a potential role of GDE2-released EVs in neurodegeneration." (PMID 39272985, 2024). "In addition, we investigated whether the mRNA and protein expression of CAP2, SAP97, and ADAM10 are also affected in patients with neurodegenerative disorders such as Parkinson’s Disease (PD) and Alzheimer’s Disease (AD), which are also characterized by spine defects." (PMID 35163460, 2022). "The bta05010 KEGG metabolic pathway was annotated for the gene ADAM10 (position 51 Mb on the BTA10) and is related to the Alzheimer disease." (PMID 35052358, 2021). "ADAM10 is one of the proteolytically active ADAM members and has been studied in particular due to its potential role in the pathogenesis of Alzheimer’s disease, since amyloid precursor protein is one of the substrates of ADAM10." (PMID 26325204, 2015). "Thus, how ADAM10 gains catalytic competence in vivo by complete removal of the propeptide is unknown, but this is an important question in the understanding of Alzheimer’s disease where the α-secretase activity is outweighed by pathological cleavage by β- and γ-secretases." (PMID 22940918, 2013). "In a transgenic mouse model of Alzheimer disease (AD), cleavage of the amyloid precursor protein (APP) by the α-secretase ADAM10 prevented amyloid plaque formation, and alleviated cognitive deficits." (PMID 19196476, 2009). "sAPPα, the non-amyloidogenic product of ADAM10, has been well characterized for its neuroprotective roles and its therapeutic potentials in Alzheimer’s disease." (PMID 38956605, 2024). "Apart from the “Total 17 NAbs” cluster, the NAb clusters for “Alzheimer’s disease” (SORL1, ADAM10, CLU and TREM2) and “Neurodegenerative disease” (SORL1, ADAM10, CLU and TREM2 and WWOX) showed the best diagnostic performance for AD with sensitivity (against 95% specificity) up to 0.759." (PMID 36922858, 2023). "Besides EGCG, there are various commercially available ADAM10 enhancers/activators, of which Acitretin (ADAM10 enhancer) is an FDA-approved drug for psoriasis and is also now under phase II clinical trial for Alzheimer's disease." (PMID 36185601, 2022). "ADAM10 has a protective role in Alzheimer's disease as a putative α-secretase that promotes non-amyloidogenic cleavage of amyloid precursor protein, preventing amyloid beta formation." (PMID 34277682, 2021). "Finally, it would be therapeutically desirable to activate TspanC8/ADAM10 in some instances, for example, to induce cleavage of APP to treat Alzheimer’s disease." (PMID 34201472, 2021). "ADAM10 is the main α-secretase that cleaves APP (amyloid precursor protein) in the non-amyloidogenic pathway inhibiting the formation of β-amyloid peptide, whose accumulation and aggregation leads to neuronal degeneration in Alzheimer’s disease (AD)." (PMID 29382156, 2018). "In Alzheimer’s disease ADAM-10 could have beneficial properties, as APP processing by ADAM-10 reduces both APP cleavage by BACE1 and β-amyloid generation, a physiologically active APP fragment clumping into neurotoxic aggregates." (PMID 27120619, 2016). "For example, for Alzheimer’s disease the activators or potentiators of ADAM10 activity might be useful to increase non-amyloidogenic processing of APP thus decreasing amyloid plaque formation in CNS." (PMID 32435655, 2020). "Unlike the ADAM10, which is best taken in the early stages of cognitive impairment, the CNTF can rescue severe and late stages of cognitive impairment in Alzheimer’s disease." (PMID 39588547, 2024).
Alzheimer disease (continued). "ADAM10 is the main α-secretase that participates in the non-amyloidogenic cleavage of amyloid precursor protein (APP) in neurons, inhibiting the production of β-amyloid peptide (Aβ) in Alzheimer’s disease (AD)." (PMID 33670873, 2021).
breast carcinoma (72 papers, 2008 to 2025). "Among the ADAM isoforms, ADAM9 and ADAM10 have been identified in EVs associated with breast cancer." (PMID 40214422, 2025). "Taken together, these results suggest that the DPAGT1/ADAM10 axis is associated with poor prognosis of patients with HER2+ breast cancer." (PMID 37463446, 2023). "In clinical breast cancer cases, a high ADAM10 expression in pre-NACT samples was strongly associated with poorer response to NACT and shorter overall survival." (PMID 33413403, 2021). "In the literature, APP is a well-established cancer biomarker, a target of ADAM10, and has been strongly linked with breast cancer growth, metastasis and migration." (PMID 34193143, 2021). "Moreover, a study of clinical breast cancer patients receiving neoadjuvant chemotherapy treatment (NACT) demonstrates that higher ADAM10 protein level before NACT was associated with poor response to NACT and shorter overall survival." (PMID 33413403, 2021). "It indicates that ADAM10 is associated with chemo-resistance in breast cancer especially in TNBC." (PMID 33413403, 2021). "We should also keep in mind that CD9-deficiency leads to decreased expression of ADAM10, a metalloproteinase that could play a role in breast cancer progression." (PMID 25762645, 2015). "However, trastuzumab treatment led to an increase of ADAM10 level in HER2 positive breast cancer patients and higher basal ADAM10 expression was associated with poorer trastuzumab treatment response and relapse-free survival." (PMID 24952873, 2014). "Overall, these findings indicate that ADAM10 supports breast cancer cell survival via cell death inhibition and chemoresistance while supporting breast cancer cell progression via the promotion of proliferation, migration, and invasion." (PMID 40214422, 2025). "Adding a dual ADAM10/17 inhibitor to inhibit the shedding of HER ligands in combination with trastuzumab only showed a modest decrease in the cell viability of HER2-low breast cancer cells and PDOs." (PMID 38600326, 2024). "One of the first inhibitors INCB3619, a dual ADAM10/17 inhibitor, was investigated and showed anti-cancer activity in animal model of breast cancer." (PMID 38600326, 2024). "The dual ADAM10/17 inhibitor as a monotherapy or in combination with trastuzumab showed only a slight decrease in the cell viability of these HER2-low breast cancer cells compared to trastuzumab alone." (PMID 38600326, 2024). "ADAM10 targeting has also been explored in cancers, such as glioblastoma, Hodgkin lymphoma, non-Hodgkin lymphoma, multiple myeloma, and breast cancer." (PMID 38399697, 2024). "We also proceeded to investigate the effect of dual ADAM10/17 inhibition using INCB7839 in the panel of PDOs in view of the results seen in HER2-low breast cancer cells." (PMID 38600326, 2024). "Elevated levels of ADAM10 have been associated with poor prognosis in cancers such as glioblastoma and breast cancer, and ADAM10 shows potential as a pan-cancer biomarker." (PMID 38399697, 2024). "According to the research reported, the expression level of ADAM10 is elevated in pan-cancer, including lung cancer, pancreatic cancer, colon cancer, and breast cancer and so on." (PMID 39346916, 2024). "We also investigated the combination of trastuzumab with a dual ADAM10/17 inhibitor in these breast cancer cells and only observed minimally additive or synergistic effects, consistent with the PDOs findings." (PMID 38600326, 2024). "Here, we examined if the additional inhibitor to ADAM10 and γ-secretase will enhance the efficacy of trastuzumab on p75HER2 production in breast cancer cells." (PMID 39273024, 2024). "IHC statistical analysis revealed that high expression of ADAM10 was positively associated with shorter RFS and OS, and that ADAM10 expression correlated positively with DPAGT1 level in the 170 HER2+ breast cancer specimens." (PMID 37463446, 2023). "Immune-histochemical staining for ADAM10 in breast cancer tissues of 94 patients receiving NACT also was performed." (PMID 35163586, 2022).